CD4 (CD4 molecule)
Diseases named in the same sentence as CD4 in open-access papers (continued):
Sharing a sentence is not in itself a finding about the gene and the disease.
melanoma (continued). "Based on our previous clinical and in vitro studies, we designed an antigen-engineered DC vaccine trial to promote a polyclonal CD8+ and CD4+ T cell response against three shared melanoma antigens." (PMID 31014399, 2019). "Based on the identified correlations, we characterized the production of KYN, 3-HK, and KYNA in vitro using melanoma-derived cell lines and primary CD4+ CD25− T-cells." (PMID 31434983, 2019). "Such functionality has been previously proposed in a model of melanoma, wherein antitumor activity was solely dependent on transferred CD4+ T cells." (PMID 31362778, 2019). "In the inflamed TME, the stromal tissue surrounding the melanoma cells is enriched in CD4+ and CD8+ cells but they are hyper-exhausted." (PMID 31750245, 2019). "In the B16 melanoma model, IL-35 blockade resulted in inhibition of tumor growth, increased infiltration of CD4+ and CD8+ effector T cells in tumor tissue, TdLNs, and non-TdLNs." (PMID 31681327, 2019). "We found that OXPHOS was the most important metabolic pathway distinguishing T cell subtypes: CD4+ T cells exhibited significantly higher levels of OXPHOS compared to CD8+ T cells in both melanoma (GSEA p-value = 0.002) and HNSCC (GSEA p-value < 0.001)." (PMID 31434891, 2019). "Our data now expand the insights into tumor-associated T-cell diversity by showing that not only CD8+ but also CD4+ T cells which had experienced antigen-driven clonal expansion are distributed through blood circulation of melanoma patients." (PMID 31275310, 2019). "Instead, if naïve CD4+ T cells were separated from melanoma cells or tumor-derived fibroblasts using the transwell system, the generation of Th17 cells from naïve CD4+ T cells was significantly decreased compared to coculture." (PMID 30800130, 2019). "In B16 melanoma, administration of DCs loaded with apoptotic B16 cells to mice promoted the development of a long-lived functional anti-tumor CD4+ T cell compartment that produced IFN-γ upon stimulation." (PMID 31379821, 2019). "After the prediction in TIMER database, it is suggested that the immune infiltrates of B cell, CD8+ cell, CD4+ cell, macrophage, neutrophil, and dendritic cell correlate with melanoma patient survival." (PMID 31681565, 2019). "The spectratypes of CD4+ T cells from melanoma patients showed significantly greater numbers of distinct peaks than healthy controls (p = 0.0018), indicating overrepresentation of TCR rearrangements with a particular length." (PMID 31275310, 2019). "Of note, CpG site 13 showed increased LGALS9 methylation in CD8+ T cells not only compared to melanoma and melanocyte cell lines but also compared to distinct leukocytes including the CD4+ T lymphocytes." (PMID 31747929, 2019). "We compared the CTLA-4 protein expression in Tregs (CD4+ Foxp3+) from these patients to five ipilimumab-treated melanoma patients, since they also have disruption of the CTLA-4 pathway and can experience a wide array of autoimmune complications." (PMID 31156616, 2019). "Patients with melanoma or glioblastoma receiving personalized neoantigen vaccines appear to favor CD4+ over CD8+ T-cell responses against the immunizing peptides, even though these were predicted and prioritized using HLA-I binding algorithms." (PMID 31293573, 2019). "Signaling mediated by C3a contributes to melanoma tumorigenesis by inhibiting neutrophil and CD4+ T-cell responses." (PMID 31031765, 2019). "In the blood of melanoma patients, our spectratyping analyses now precisely reveal substantial repertoire restrictions with clonal T-cell expansions in both CD4+ and CD8+ T cell subsets." (PMID 31275310, 2019). "Antibody of anti–programmed death 1, situated on the surface of CD4+ cells, had been verified to prove the clinical outcomes of patients with melanoma." (PMID 31608101, 2019). "We evaluated Tregs using the surface marker set CD4 + CD127-/lowCD25+ in T-cells harvested from melanoma patient PBMC and treated with ACY-1215 or ACY-241." (PMID 30728070, 2019).
melanoma (continued). "A small but significant fraction of the CD4+ T-cell line recognized a NY-ESO-1+DP*04+ SK-MEL-37 melanoma cell line, indicating the presence of TR-CD4 cells." (PMID 30626427, 2019). "Several studies showed that increased frequencies of memory T cells or decreased frequencies of naïve-phenotype CD4+ or CD8+ T cells in the blood were correlated with better outcomes in anti-CTLA4-treated melanoma patients." (PMID 31275310, 2019). "The clonal CD4+ T-cell expansions likely manifest higher frequencies of central memory CD4+ T cells which had been observed in blood of two melanoma patients who responded well to PD-1 blockade." (PMID 31275310, 2019). "Various clonal TCRs in CD8+ and CD4+ blood T cells from melanoma patients were identified, while the same approach did not detect redundant TCRs in the TCR Vβ-gene families of healthy individuals (data not shown)." (PMID 31275310, 2019). "In a BRAF-mutated model of mouse melanoma, the BRAF-inhibitor PLX4720 selectively decreased the number of CD4+Foxp3+ Treg cells and of CD11b+Gr1+ myeloid-derived suppressor cells (MDSC) in the tumor microenvironment." (PMID 31762942, 2019). "Thirdly, we compared the methylation status of HAVCR2/TIM-3 and LGALS9 with isolated monocytes, granulocytes, B cells, CD8+ T cells, and CD4+ T cells from healthy donors and melanocyte and melanoma cell lines." (PMID 31747929, 2019). "As melanoma is very immunogenic, we evaluated the presence of CD4+ and CD8+ T cells in metastatic lungs of animals treated with vehicle or DABK." (PMID 31607931, 2019). "To this end, we investigated the changes in the dLN, PBL, and tumor CD8+ T cell repertoires following anti-CD4 mAb treatment using unbiased high-throughput TCR sequencing (TCR-seq) in a B16F10 mouse subcutaneous melanoma model." (PMID 30733724, 2018). "More recently, transcriptomic comparison of CD4+ T cells at baseline and antigen specific CD4+ T cells after neoantigen vaccination in melanoma patients revealed significant induction of effector and memory T cell gene expression programs including Tbx21." (PMID 29423108, 2018). "In this study, we conducted high-throughput TCR-seq on CD8+ T cells sorted from the dLN, PBL, and tumor in a B16F10 mouse melanoma model to investigate the effects of anti-CD4 mAb treatment on the CD8+ T cell repertoire." (PMID 30733724, 2018). "In the present study, we treated established tumors with melanoma-specific adoptive CD4+ T cell transfer and costimulation via OX40 or CTLA-4 blockade." (PMID 30400822, 2018). "In conclusion, we show that CD4+ T cells of young melanoma patients show signs of activation, whereas these signs are less clear in CD4+ T cells of old patients." (PMID 29546435, 2018). "At 14 days from melanoma tumor cell injection, as consistent, we found significantly decreased number of pleural colonies in the lung of CD4-Chi3l1 KO mice with reduced tumor infiltration around the vessel." (PMID 29403003, 2018). "High PD-L1 expression on peripheral T cells (CD4+ and CD8+) has been shown to be associated with worse PFS and OS for CTLA4ab treatment of melanoma." (PMID 30002656, 2018). "Serial immune analysis completed on 10 melanoma patients demonstrated CD4 and CD8 T cell responses against 58% of vaccine peptides as measured by via IFNγ ELISpot." (PMID 30400822, 2018). "This assumption was based on earlier studies demonstrating that cutaneous melanoma is associated with multiple neoantigen-specific CD4+ and CD8+ T cells, presumably as the result of a high mutational burden in melanoma cells." (PMID 30560089, 2018). "The slices of 4T1 and melanoma models exhibited an increased number of CD4, CD8, and CD86 in the Tα1-Fc group compared with that in the Tα1 group." (PMID 30120362, 2018). "There was a significant increase in the frequency of CD8+ T cells, with a corresponding decrease of CD4+ T cells, among the PBMCs that had been co-cultured with melphalan-exposed melanoma cells." (PMID 30560089, 2018).
melanoma (continued). "The indirect recognition mechanism of Th1-polarized CD4 T cells has been comprehensively investigated in a melanoma model as well." (PMID 29032503, 2018). "There is a previously published single case study in which significant increases in CD4 T-cell counts were observed after treatment with ipilimumab in an HIV-1-infected patient who also had melanoma." (PMID 29879143, 2018). "We determined if CD4+ T cells of young and old melanoma patients show increased expression of the checkpoint molecules PD-1 and CTLA-4." (PMID 29546435, 2018). "Absolute numbers of CD4+ T cells were decreased in young and old melanoma patients when compared to the age-matched control groups." (PMID 29546435, 2018). "Young melanoma patients showed an increase of CD161 expressing CD4+ T cells compared to young controls." (PMID 29546435, 2018). "Although the CD4+ T cells of young melanoma patients showed clear signs of activation and proliferation, these subjects all had metastatic disease." (PMID 29546435, 2018). "In a later study, they also identified three HLA-DRB4*0101–0103, MHC class II epitopes that were recognized by CD4+ T lymphocytes from two melanoma patients." (PMID 29770138, 2018). "Remarkably, we observed low proportions of CD4+ TNaive cells in young melanoma patients in comparison to age-matched controls." (PMID 29546435, 2018). "The percentages of all CD4+ T-cell differentiation subsets were similar in old melanoma patients and age-matched controls." (PMID 29546435, 2018). "The notion of an ongoing immune response in young melanoma patients is further substantiated by the decrease of thymic emigrant CD4+ TNaive cells and the concomitant expansion of TCM and inflammatory TEM when compared to age-matched controls." (PMID 29546435, 2018). "For example, ICOSL expressed on mesenchymal stem cells, and melanoma cells, can promote the induction and expansion of IL-10-producing CD4+ T cells." (PMID 30319662, 2018). "Our findings indicate a temperate CD4+ T-cell response in the peripheral blood of old melanoma patients, whereas CD4+ T cells of young melanoma patients showed prominent signs of activation, proliferation, and differentiation." (PMID 29546435, 2018). "It should be noted that this dysfunction-associated phenotype occurred only in mice with relapsing melanoma and suggests that exhaustion of tumor-specific CD4 T cells contributed to recurrence of melanoma." (PMID 29032503, 2018). "In M-ILP treated melanoma patients, T cell activation was evident by increased expression of the activation marker HLA-DR on CD4+ and CD8+ T cells along with induction of regulatory T cells." (PMID 30560089, 2018). "The effect of combination therapy with IL PV-10 and PD-1 blockade is mediated by CD8+ T cells, and depletion of either CD4+ T cells or CD4+CD25+ Tregs enhances anti-tumor immunity in the M05 melanoma model." (PMID 29694419, 2018). "In stage I-III melanoma patients, high expression of CXCR4 in circulating CD4+CD45RA+ was associated with prolonged disease free survival." (PMID 30420855, 2018). "To determine if 17-AAG treatment can enhance the immune response of adoptively transferred cytotoxic CD4+ T cells against established melanoma tumors, we subcutaneously injected C57BL6 mice with B16.F10 mouse melanoma cells." (PMID 29481571, 2018). "We investigated if the lower number of CD4+ T cells in melanoma patients resulted from a decline of particular T-cell differentiation subsets." (PMID 29546435, 2018). "In the total cohort of BM as well as in the subcohort of melanoma BM the positive prognostic marker CD74 on tumor cells is nevertheless significantly associated with increased numbers of TILs (including CD3-, CD4- and CD8-positive TILs)." (PMID 29490700, 2018). "–8 of 12 patients achieved a complete or partial response.–5 of 7 melanoma patients had a complete or partial response.–Greater frequency of proliferating CD4(+) T-cells in responding patients." (PMID 29644213, 2018).
melanoma (continued). "More recently, it has been reported that anti-CTLA-4 therapy induces the expansion of melanoma-infiltrating ICOS+ TH1-like CD4+ T cells as well as exhausted-like CD8+ T cells." (PMID 29494517, 2018). "We proposed a method of shortened ex vivo expansion using Th17 cells to treat melanoma using the TRP-1 transgenic mouse model in which CD4+ T cells express a TCR that recognizes tyrosinase-related protein 1 on melanoma." (PMID 30400835, 2018). "Percentages of HLA-DR expressing cells were increased among CD4+ T cells of young melanoma patients when compared to those in young controls." (PMID 29546435, 2018). "We next correlated the PDL1+ melanoma or macrophage cell location with %CD8+ or %CD4+ T cells (mIHC) and their location (IT or stroma)." (PMID 30042403, 2018). "In conclusion, our findings indicate that circulating CD4+ T cells in young patients with metastatic melanoma are quite strongly activated, whereas CD4+ T cells of old melanoma patients seem relatively dormant." (PMID 29546435, 2018). "It has been reported that DC1 producing large amounts of IL-12 family members are able to rescue patients’ Th1-type anti-melanoma CD4+ T-cell responses in vitro." (PMID 30314368, 2018). "To evaluate the contribution of CD4+ and CD8+ T cells to the observed decreased tumor outgrowth, we challenged Nr2f6−/− subcutaneously with 1×105 B16-OVA melanoma cells and treated them with CD4+ and CD8+ depleting antibodies." (PMID 29670099, 2018). "Depleting YUMM2.1-bearing animals of CD4 cells completely abrogated the response to PD-1, suggesting a prominent role of CD4 T cells in this melanoma model." (PMID 29032503, 2018). "In this setting, co-culture of PBMCs with melanoma cells appeared to decrease the expression of HLA-DR on CD4+ T cells." (PMID 30560089, 2018). "We studied the activation status of CD4+ T cells in the young and old melanoma patients by determining the percentage of HLA-DR expressing cells." (PMID 29546435, 2018). "Proportions of CD4+ TNaive cells in young melanoma patients were actually similar to those in old patients and controls." (PMID 29546435, 2018). "Proportions of CD4+ TNaive cells were decreased in young melanoma patients when compared to age-matched healthy controls." (PMID 29546435, 2018). "The percentage of CTLA-4 expressing cells CD4+ T cells was similar in melanoma patients and controls, both in young subjects and old subjects." (PMID 29546435, 2018). "Although it is unclear if this premature contraction has developed due to or prior to disease, it likely compromises CD4+ T-cell immunity against the full spectrum of melanoma antigens." (PMID 29546435, 2018). "Most of the antigens expressed in melanoma tumors are recognized by CD4+ and CD8+ T cells, which have cytotoxic functions and are capable of infiltrating tumor sites." (PMID 29581861, 2018). "The percentage of Ki-67 expressing cells was higher in CD4+ T cells of young melanoma patients than those of age-matched healthy controls." (PMID 29546435, 2018). "In contrast, proportions of post-thymically expanded CD31– central CD4+ TNaive cells were comparable in young and old melanoma patients versus the age-matched controls." (PMID 29546435, 2018). "Proportions of HLA-DR expressing CD4+ T cells in young melanoma patients resembled those in old patients and controls." (PMID 29546435, 2018). "Percentages of memory CD4+ T cells tended to be increased in young melanoma patients compared to young controls." (PMID 29546435, 2018). "Other studies of malignant glioma and melanoma have shown that this treatment restores CD4+ and CD8+ effector T cells by abrogation of the immunosuppressive effect of Tregs which express these inhibitory markers and produce immunosuppressive IL-10 cytokine." (PMID 29610255, 2018). "In sum, sixteen B16 melanoma-reactive T cell hybridomas were generated from CD4+Teffs and Tregs, sorted from tumor mass or tumor draining lymph nodes of both untreated and DTA-1 treated TCRmini mice." (PMID 28638937, 2017).
melanoma (continued). "As it has been postulated that melanoma cells can be eradicated directly by CD4+ T cells, it would be interesting to use our B16F10/M2KO cell line as a control in tumor rejection experiments." (PMID 28301575, 2017). "In 2010, they proposed models of a tumor, CD4+ T cells, and cytokine interactions to discuss the role of CD4+ T cells in melanoma rejection, where CD4+ T cells were separated into Th1 and Th2 cells." (PMID 29250133, 2017). "Primary human B cells activated in vitro with CD40 ligand and subsequently pulsed with melanoma tumor antigens, efficiently processed and presented MHC class II-restricted peptides to specific CD4+ T cell clones, generating melanoma-specific T cells." (PMID 28507802, 2017). "Using IL-9-eGFP mice, we observed that, CD4 expressing IL-9-eGFP were present in B16F10 melanoma tumour bed." (PMID 29233972, 2017). "In fact, this type of activity has been demonstrated previously with a high-affinity melanoma antigen tyrosinase-reactive TCR expressed by CD4+ T cells." (PMID 29123516, 2017). "In humans, we found circulatory IL-10 strongly elevated in late stages of melanoma positively correlating with the circulatory elevated T lymphocyte CD4+ and CD25+ with FOXP3 expression." (PMID 29318162, 2017). "Data obtained suggested that GA-DM treatment increases HLA class II Ag presentation and CD4+ T cell recognition of melanoma tumor cells." (PMID 29399381, 2017). "Granulocytic or monocytic MDSC derived from mice containing B16-F10 melanoma tumors appear to suppress proliferation in the setting of peptide presentation from DC to CD4+ T cells by 30.3 ± 2.9% and 20.3 ± 2.2%, respectively." (PMID 29133913, 2017). "In four out of six MLTC using the PBMC and melanoma cells of different patients, CD4+ T cell depletion increased the absolute number of tumor-reactive CD8+ T cells obtained after 4 weeks of MLTC." (PMID 28401257, 2017). "Use of VSV as the vector expressing TAAs from the cDNA library of melanoma successfully induced IL-17 recall response of tumor specific CD4+ T cells and eradicated melanoma tumors." (PMID 28567163, 2017). "NK1.1− CD4+ NKG2D+ or NK1.1+ CD4+ NKG2D+ cells were incubated with melanoma target cells, B16‐MICA, which ectopically expressed MICA of B16 cells." (PMID 28224733, 2017). "In melanoma, some CTLs and some CD4 T cells recognised peptides from proteins specifically expressed in the melanoma cells." (PMID 28695288, 2017). "Patients with cervical intraepithelial neoplasia grade 1 13, 14, colon cancer 15 and melanoma who were pre‐treated with a multityrosine kinase inhibitor (sorafenib) also exhibit enhanced frequencies of CD4+ NKG2D+ T cells." (PMID 28224733, 2017). "Our study demonstrated that primary melanoma treated by the cryo-thermal therapy produced long-term tumor-free survival that was dependent on CD4+ T-cell orchestrating antitumor immune memory response." (PMID 28333145, 2017). "Another study showed that combined anti-CD4+ anti-PD-1/PD-L1 mAb therapy synergistically mediated B16-F10 melanoma or C26 colon cancer rejection, in syngeneic mice." (PMID 29070883, 2017). "Adenovirus, VSV and HSV engineered to express soluble B7 or CD40L exhibited more effective melanoma regression and significantly enhanced CD4+ and CD8+ T-cell infiltration." (PMID 28567163, 2017). "CD4+TIM3+ was increased from 12% (naïve lymph nodes) to 19% (draining lymph node), other IRs phenotype such as CD4+BTLA+ (38%), CD4+2B4+ (35%), CD4+LAG3+ (27%) was also increased in draining lymph node of melanoma-bearing mice than naïve mice." (PMID 27447564, 2016). "In two independent cohorts of anti-PD-1-treated melanoma patients, MHC-II positivity on tumour cells is associated with therapeutic response, progression-free and overall survival, as well as CD4+ and CD8+ tumour infiltrate." (PMID 26822383, 2016).